CASP1 (caspase 1)
Diseases named in the same sentence as CASP1 in open-access papers (continued):
Sharing a sentence is not in itself a finding about the gene and the disease.
diabetic nephropathy (35 papers, 2012 to 2025). "Several studies have suggested a potential association between CASP-1 activation and conditions such as ischemia–reperfusion injury, diabetic nephropathy, and the progression of renal fibrosis." (PMID 38229085, 2024). "In the context of diabetic kidney disease, studies have shown that excessive cell pyroptosis mediated by caspase-1-associated canonical cleavage of GSDMD (as well as caspase-11/4 non-canonical GSDMD cleavage) promotes podocyte damage and renal immune cell infiltration." (PMID 39920111, 2025). "The caspase-1 inhibitor VX-765 emerges as a promising therapeutic candidate for mitigating the progression of diabetic nephropathy, as it effectively suppresses caspase-1-mediated pyroptosis, renal inflammation, and fibrosis in diabetic mice." (PMID 40891136, 2025). "(+)-Catechin also suppresses NLRP3-associated inflammation in the kidney, as demonstrated by reductions in NLRP3, ASC, AIM2, caspase 1, IL-1β, and IL-18 expression in mice with diabetic nephropathy and palmitic acid-treated HK-2 cells." (PMID 41020857, 2025). "In a rat model of diabetic nephropathy, maresin-1 exerted a protective effect on glomerular mesangial cells by decreasing the expression of ROS, NLPR3, caspase-1, and IL-1β, which are responsible for the development of diabetic nephropathy." (PMID 40731875, 2025). "Inhibition of caspase-1 expression can reduce renal tubular cell pyroptosis and alleviate Diabetic Nephropathy (DN) kidney damage." (PMID 37418795, 2023). "Reduced gene expression of NLRP3 and caspase-1 (signal 1) by minocycline has also been described in mouse models of diabetic nephropathy or Huntington disease." (PMID 35130879, 2022). "MALAT1 overexpression catalyzed pyroptosis in diabetic nephropathy to accelerate kidney impairment with the involvement of increased IL‐1β, IL‐18, Caspase-1, and GSDMD." (PMID 36243708, 2022). "Caspase-1-dependent inflammasome activation has a crucial function in the establishment of diabetic nephropathy." (PMID 35626360, 2022). "NLRP3 or caspase-1 gene knockout and caspase-1 inhibition blocked or even reversed the progression diabetic nephropathy in mice." (PMID 31737627, 2019). "Previous studies of our research group have found that AS-IV may improve cellular pyroptosis by down-regulating the expression of GSDMD and Caspase-1 in renal tissues of diabetic nephropathy." (PMID 38820434, 2024). "In an STZ-induced rat model of diabetic nephropathy (DN) with hyperuricemia and dyslipidemia, overexpression of NLRP3 inflammasome components [apoptosis-associated speck-like protein (ASC) and caspase-1] has been found to be associated with elevated IL-1β and IL-18 levels." (PMID 34267672, 2021). "Hence, the repression of NLRP3 inflammasome contributes to the function of coptisine on diabetic nephropathy, maybe through interacting with caspase-1 directly or modulating the Nrf2 or NF-κB pathways indirectly." (PMID 37197172, 2023). "The subsequent autocleavage and activation of caspase-1 in turn results in the processing of pro-IL-1β to its mature form, which then leads to the induction of other proinflammatory genes, eventually promoting the oxidative stress and inflammation present in diabetic nephropathy." (PMID 26881256, 2016). "In diabetic nephropathy mice, significant expression of NLRP3 and caspase-1 is observed in glomerular endothelial cells and podocytes." (PMID 41357229, 2025). "In immortalized mouse podocytes, high glucose can induce podocyte pyroptosis by up-regulating NLRP3, ASC, caspase-1, and GSDMD(N), while in the kidneys of diabetic nephropathy mice, markers of pyroptosis are also significantly increased." (PMID 39850113, 2025). "Over the past five years, key topics in this field have revolved around the “heart”, “damage”, “caspase 1 activation”, “NLRP3”, and “diabetic kidney disease”." (PMID 39717099, 2024).
diabetic nephropathy (continued). "In diabetic nephropathy (DN) patients, DN mouse models, and in vitro high glucose (HG)-induced HK2 cell models, increased expression of pyroptosis marker proteins, cleaved-caspase-1 and GSDMD-NT, has been observed in tubular cells." (PMID 39659523, 2024). "In a mouse model of diabetic nephropathy, maresin-1 exerted a protective effect on glomerular mesangial cells by decreasing the expression of ROS, NLPR3, caspase-1, and IL-1β, which are responsible for the development of diabetic nephropathy." (PMID 35163291, 2022). "Inhibiting oxidative stress and inflammatory reactions associated with apoptosis, significantly reduceing levels of Caspase-1, IL-1β, and NLRP3 and improving GBM thickening and inflammatory cell infiltration, thereby suppressing the development of diabetic nephropathy." (PMID 40568564, 2025). "In diabetic nephropathy models, both in vivo and in vitro, MCC950 attenuates glomerular basement membrane thickening, podocyte injury, and renal fibrosis by suppressing the NLRP3/caspase-1/IL-1β signaling axis." (PMID 41357229, 2025). "By blocking the NLRP3/caspase-1/IL-1 pathway and lowering urinary NGAL levels in mice with a model of diabetic nephropathy, researchers demonstrated that MCC950 might significantly alleviate diabetic chronic kidney injury." (PMID 38114914, 2023). "The extent of renal damage in diabetic mice was identical to wild-type mice when bone marrow from Nlrp3-/- and Caspase-1-/- mice was transplanted in db/db mice, and induction of the NLRP3 inflammasome originating from intrinsic renal cells worsened diabetic nephropathy (DN)." (PMID 35204131, 2022). "At present, no previous studies have related the levels of this enzyme with adenosine signaling in diabetic nephropathy, but it is suggested that the use of the ADORA3 antagonist could have a major role on caspase 1 activation, which is a necessary event in the generation of interleukins." (PMID 31540220, 2019). "A study of traditional Chinese medicine for the treatment of diabetic nephropathy revealed that ginsenoside Rh2 could ultimately alleviate diabetic nephropathy by inhibiting LMP, reducing the expression of CTSB and cathepsin L, and inhibiting caspase-1-mediated pyroptosis." (PMID 40129990, 2025).
asthma (32 papers, 2013 to 2025). "Increased caspase-1 activity in immune cells or bronchial tissue is a hallmark of steroid-resistant asthma, often triggered by viral infections or pollutants, implicating it in the pathogenesis of severe exacerbations." (PMID 41394843, 2025). "Single nucleotide polymorphisms (SNPs) in NLRP3 inflammasome and caspase-1 have been linked to the increase in childhood asthma susceptibility." (PMID 39611173, 2024). "During asthma process, miR-423 downregulated the expression of interleukin-1β/NOD-like receptor thermal protein domain associated protein 3/Caspase-1 inflammasome signaling by targeting PINK1 in lung cells." (PMID 39276929, 2024). "The assembled NLRP3 inflammasome cleaves pro-Caspase-1 proteolysis into mature Caspase-1 to promote the release of the inflammatory factors IL-1β and IL-18, mediating immune imbalances in asthma." (PMID 38029078, 2023). "According to research, Acinetobacter baumanni activates the Nod-like receptor NLRP3 via caspase-1 to promote the release of IL-1β and TNFα from macrophages, thereby inducing asthma." (PMID 37180436, 2023). "Expression of ASC and pro-caspase-1 proteins was stable and comparable between controls and patients with asthma." (PMID 37087523, 2023). "Previous studies have shown that elevated caspase-1 and IL-1β can be detected in mouse models of asthma, and increased IL-18 can also be detected in the sputum of asthmatic patients and is associated with asthma severity." (PMID 36081945, 2022). "Our findings showed that inhibiting the NLRP3/caspase-1/IL-1 pathway helped rebalance Th17/Treg cells in asthma patients." (PMID 35664352, 2022). "Even more, Alt a 1-asthmatic mice showed an increase of ORMDL-3 and caspase-1 in the asthmatic mice, both markers related to severe asthma." (PMID 35844541, 2022). "Referring to caspase-1, it can induce the T2 cytokines production inducing the asthma exacerbations." (PMID 35844541, 2022). "Recent reports have shown that NLRP3-related inflammatory response is a key driver of asthma pathogenesis and the allergen Der f1 induces bronchial asthma by mediating caspase-1-dependent pyroptosis through the NLRP3 pathway." (PMID 35967302, 2022). "Another study showed that the levels of NLRP3 and caspase-1 in the airway of patients with a neutrophilic subtype of asthma were higher than those of healthy people." (PMID 36248872, 2022). "Exposure to gastric bacteria H. pylori can also drive asthma protection by inducing IL-18 in dendritic cells through the NLRP3/CASP1/IL-18 axis." (PMID 33546184, 2021). "The SNPrs11078928, which prevents the splicing of exon 6, and thus abolishes the expression of GSDMB isoform 3, was associated with decreased asthma risk, implying that caspase-1-induced, GSDMB-mediated pyroptosis perhaps plays a role in asthma pathogenesis." (PMID 33406603, 2021). "It has been demonstrated that the expression of NLRP3, caspase-1 and IL-1β is enhanced in the lungs of asthma patients and allergen-induced asthmatic mice compared to healthy controls." (PMID 34413860, 2021). "More recently, RV infection was found to increase caspase 1 expression to a greater extent in asthmatic PBECs than in normal cells, and in a house dust mite murine model of asthma exacerbations, caspase 1 knockout mice had reduced Th2 responses to poly(I:C)." (PMID 30333178, 2019). "Western blot analyses showed that the levels of NLRP3 and caspase-1 in BAL fluids from the patients with asthma were significantly higher than the levels in healthy subjects." (PMID 25356867, 2014). "Thus, the role of NLRP3/caspase-1 signaling in asthma appears to depend on the inflammatory phenotype of asthma." (PMID 39611173, 2024). "However, the blockade of the NLRP3/caspase-1 axis attenuated the bronchial neutrophilic inflammation in mice exposed to toluene diisocyanate (TDI), implying that the NLPR3/caspase-1 signaling promotes neutrophilic inflammation in asthma." (PMID 39611173, 2024).
asthma (continued). "Caspase-1- or NLRP3-deficient mice exposed to HDM exhibited enhanced eosinophil recruitment, and exacerbated airway inflammation, suggesting that the NLPR3/caspase-1 axis restrain eosinophilic inflammation in asthma." (PMID 39611173, 2024). "The mRNA expressions of TLR4, MyD88, nucleotide-binding oligomerization domain-like pyrin domain-containing protein 3 (NLRP3), caspase-1, interleukin (IL)-18, and IL-1β in induced sputum cells of patients with asthma were upregulated and related to the mRNA expression of MUC1." (PMID 37880668, 2023). "Moreover, among the various phenotypes of asthma, the expression of NLRP3, caspase-1, caspase-4, and other PRGs in neutrophil asthma significantly increases and NLRP3 inflammatory bodies can drive animal asthma models to produce glucocorticoid resistance." (PMID 35967302, 2022). "Given this background, the NLRP3/caspase-1/IL-1β pathway apparently plays an important role in the pathogenesis of asthma, but the precise effects of NLRP3 inflammasome activation on airway inflammation in an OVA-induced murine model of neutrophilic asthma remain elusive and deserve investigation." (PMID 35664352, 2022). "Furthermore, asthma subtypes with upregulated NLRPs and caspase-1 exhibit high glucocorticoid use and poor asthma control." (PMID 35967302, 2022). "While further research is needed to pinpoint the exact mechanism, these results provide light on the etiology of neutrophilic asthma and indicate that blocking the NLRP3/caspase-1/IL-1 pathway might be a viable asthma treatment target." (PMID 35664352, 2022). "Interestingly, during HDM-induced asthma, caspase-1 activation and IL-1β maturation were upregulated only in alveolar macrophages, not in neutrophils or DCs, indicating that AMs contributed most to HDM-induced inflammasome activation." (PMID 34413860, 2021). "People with asthma had more NLRP3, ASC, caspase-1, and the pro-inflammatory cytokines IL-1β and IL-18 in their bronchoalveolar lavage fluid and sputum samples." (PMID 41318536, 2025). "Mice with ovalbumin (OVA)-induced asthma presented with increased pulmonary NLRP3, caspase-1 and IL-1β expression, while the blockage of the NLRP3/caspase-1/IL-1β pathway attenuated bronchial inflammation in asthmatic mice." (PMID 39611173, 2024). "In a model of HDM-induced asthma, NLRP3 inflammasome even dampened Th2 responses through caspase-1 activation." (PMID 36189256, 2022). "The administration of MCC950 to a toluene diisocyanate-induced asthma model blocked the activation of NLRP3 and downregulated protein expression of caspase-1, IL1β, and IL18." (PMID 36189256, 2022). "Since the imbalance of Th17, Treg cells, and their related cytokines play a vital role in the progression of asthma, we investigated the effects of NLRP3 and caspase-1 inhibitors on Th17-mediated immune responses in this murine model." (PMID 35664352, 2022). "Therefore, inhibition of caspase-1/4 may be a promising therapeutic target in asthma." (PMID 36248872, 2022). "Meanwhile, the protein levels of NLRP3, ASC, Caspase-1 and Pro-Caspase-1 in lung tissue of YPFS treated OVA-sensitized asthma mice also decreased significantly in comparison with those in model group." (PMID 29311942, 2017). "Similarly, mice with OVA-induced asthma showed a significantly higher expression of NLRP3, Caspase-1, IL-1β in lung tissues, and QF can significantly downregulate the expression levels of these proteins." (PMID 36081945, 2022). "However, in our study, the expression of caspase 1 and caspase 3 was elevated after OVA-induced asthma mice were administered MDSCs." (PMID 36045657, 2022). "Activation of caspase-1 even dampens IL-33-dependent allergic asthmatic inflammation.The involvement of NLRP3 is also reported in neutrophilic asthma, another type of asthma that is often associated with non-allergic exposure." (PMID 33546184, 2021).
asthma (continued). "In addition, the protein expression levels of NLRP3, caspase-1, cleaved caspase-1, GSDMD, GSDMD-N, IL-18, and IL-1β were increased, indicating that MUC1, TLR4/MyD88/NF-κB pathway, and NLRP3-induced pyroptosis are involved in the pathogenesis of asthma." (PMID 37880668, 2023). "Likewise, we also noted downregulation of epithelial expression of caspase-1 in bronchial biopsies from healthy controls 4 days after infection, whereas it did not change in patients with asthma." (PMID 37087523, 2023). "Additionally, CAD and CAD-contained serum attenuated the up-regulated expressions of Bax, Cleaved caspase-3, NLRP3, ASC, Cleaved caspase-1, GSDMD-N, IL-18, IL-1β, TLR3, p-P65, p-IκBα, and IRF3 but increased Bcl-1 and GSDMD levels in the asthma mice and LPS-induced 16HBE cells, respectively." (PMID 36213326, 2022). "Similarly, compared to the control mice, mice with OVA-induced asthma showed a significantly higher expression of NLRP3, Caspase-1, IL-1β in the lung tissues, and the expression of these key proteins was significantly decreased in asthmatic mice treated with QF." (PMID 36081945, 2022). "Our results showed that the mRNA and protein levels of NLRP3, ASC and Caspase-1 in the lungs of OVA-induced asthmatic mice were notably down-regulated after ACG treatment, suggesting that ACG might inhibit the inflammatory response in OVA-induced asthma by suppressing the NLRP3 inflammasome." (PMID 33645621, 2021). "scRNA-seq has identified non-classical monocytes (CD14+CD16+) in severe asthma lungs that exhibit primed inflammasome states (high AIM2, CASP1)." (PMID 41394843, 2025).
colorectal cancer (32 papers, 2013 to 2025). A primary or metastatic malignant neoplasm that affects the colon or rectum. "CASP1-deficiency has been found to enhance tumor formation in mouse colorectal cancer models." (PMID 28388569, 2017). "In this regard, the ability of NLRP3 to protect against the development of colorectal cancer is attributed to the effector function of caspase-1 to mediate the secretion of IL-18." (PMID 40227443, 2025). "To investigate the specific cell death pathways activated by compound 12, we conducted Western blot analyses focused on the expression levels of caspase-3, caspase-8, and caspase-1 in HCT-116 colorectal carcinoma cells." (PMID 41155897, 2025). "FL118, a novel camptothecin anticancer drug, is found to inhibit the growth and metastasis of colorectal cancer through the NLRP3-ASC-Caspase-1 pathway by mediating the pyroptosis of SW480 and HT29 cells." (PMID 38654314, 2024). "The caspase-1 specific inhibitor, VX-765, has been reported to show protective effect in colorectal cancer." (PMID 37974278, 2023). "Consistent with the favorable effects of TNFAIP1 on caspase 1/3/7 activity in macrophages or colorectal cancer cells, we found that TNFAIP1 promoted caspase-3 cleavage and subsequent generation of the N-terminal fragment of GSDME both in vitro and in vivo." (PMID 38102610, 2023). "On the contrary, antagonists targeting NLRP3 or caspase-1 suppress the migration of colorectal cancer cells in vitro, and knockout of NLRP3 decreases liver metastasis nodes in vivo." (PMID 36932407, 2023). "Furthermore, it causes caspase-1 to become activated via NF-Kappa B, resulting in the increased expression of Snail and HK3, which is contingent upon the activation of caspase-1 in colorectal cancer." (PMID 40666174, 2025). "Moreover, CASP1 has been identified as a novel biomarker and a potential target for immunotherapy in colorectal cancer patients." (PMID 41009970, 2025). "In contrast, caspase-1-activated IL-18 protects from colorectal cancer." (PMID 36581625, 2022). "Moreover, ASC and caspase-1, as components of the inflammasome, and the downstream substrates of caspase-1; IL-1β and IL-18 were decreased in colorectal cancer cells." (PMID 34571825, 2021). "Hence, the protein downregulation of NLRP6, caspase-1 or IL-18 in epithelial tumor cells was correlated with a poor clinical outcome for colorectal cancer patients." (PMID 33255437, 2020). "Casp1-/- mice reportedly showed increased tumorigenesis in colorectal cancer." (PMID 30042341, 2018). "Transcriptomic profiling of oxaliplatin-resistant colorectal cancer (CRC) cells derived from DLD1 and HCT116 identified ALCAM activation with concurrent CD22, CASP1, and CISH suppression as key molecular features of oxaliplatin non-response." (PMID 41009436, 2025). "FL118 induces pyroptosis mediated by the NLRP3 inhibitor MCC950 and the caspase-1 inhibitor VX-765 attenuate the expression of NLRP3 and caspase-1 in colorectal cancer cells." (PMID 38654314, 2024). "To strengthen the hypothesis that caspase-1 mediated cleavage of gC1qR protein prevents its localization to mitochondria and hence critically impacts cellular metabolism, we additionally utilized the colorectal carcinoma cell line HT29-MTX in functional analyses." (PMID 33102234, 2020). "In colorectal cancer, pyroptosis-associated inflammasomes inhibit tumorigenesis, and mice lacking ASC and caspase-1 are more prone to develop colorectal cancer." (PMID 38334883, 2024). "Ex vivo, tumor grading correlated with non-mitochondrial-located gC1qR as well as with caspase-1 activation in colorectal carcinoma patients." (PMID 33102234, 2020). "We investigated the correlation between the percentage of DHA in total plasma FAs prior to a 5-FU-based chemotherapy (D0) and a change of caspase-1 activity in circulating MDSC purified on D0 compared to those purified one day after chemotherapy (D1), in patients with colorectal cancer (n = 46)." (PMID 31217433, 2019).